NOX4 (NADPH oxidase 4)
Diseases named in the same sentence as NOX4 in open-access papers (continued):
Sharing a sentence is not in itself a finding about the gene and the disease.
cancer (continued). "Still, the vast majority of genes in each genetic program of cancer progression positively correlates with NOX4 expression, therefore suggesting the involvement of NOX4 in these cellular functions." (PMID 33557266, 2021). "This is the first time, to our knowledge, that NOX4 is shown to exhibit divergent effects on apoptosis and proliferation in a Primary Pan-Cancer cohort." (PMID 33557266, 2021). "NOX4 was found to be a new genetic target for anti-cancer therapy in digestive system cancer such as GC." (PMID 35178071, 2021). "Nox4 binds to p22phox and contributes to cancer development and progression via ROS release and HIF-1α in cancer cells." (PMID 34942984, 2021). "Taken together, NOX4 contributes to the increased metastatic potential of cancer cells by tuberculous fibrosis through autophagy signaling." (PMID 33567693, 2021). "As a vital source of generation for ROS, NOX4 also plays an important role in the regulation of cancer metabolism." (PMID 34257808, 2021). "Such strong correlations with genes involved in migration suggest NOX4 is a key player in cancer cell dissemination." (PMID 33557266, 2021). "HIF-1 is a key transcription factor of angiogenesis in solid tumors including PC and NOX4 can regulate angiogenesis through HIF-1 in different cancers." (PMID 34930338, 2021). "Among the NOX family members, NOX4 is the most frequently expressed in terms of its relevance in cancer, diabetes, and cardiovascular disease 16,17." (PMID 32641980, 2020). "It is known that in contrast to the other NOXs, the NADPH oxidase NOX4 exists in the immediate environment of the nucleus and is involved in genomic instability as well as in cancer and other inflammation-related diseases." (PMID 32707664, 2020). "NADPH-oxidase NOX4, which plays an essential role in the cancer cell physiology, is likely a key participant in this process." (PMID 30867888, 2019). "These experimental evidences suggest that NOX4-mediated ROS generation can play a role in the molecular mechanisms involved in the early steps in urothelial carcinogenesis and cancer cell survival." (PMID 31191796, 2019). "The article shows that in certain cancer cells Nox4 is also involved in the re-structuring of the actin cytoskeleton, which is required for cell mobility and therefore for metastasis." (PMID 30084091, 2018). "Another possible mechanism for Nox4 inducing cancer progression includes histone modification, transforming growth factor-β and epidermal growth factor receptor (EGFR) pathway and so forth." (PMID 30513726, 2018). "Upregulation of Nox4 expression was strongly correlated with myofibroblastic-CAFs, contributing to decreased cancer-specific survival rates." (PMID 30513726, 2018). "To examine the expression of NOX4 in human tumors, we analyzed RNA sequencing data from multiple cancer types (The Cancer Genome Atlas [TCGA])." (PMID 28922779, 2018). "Recently, growing evidence confirmed the role of Nox4 in the disease progression of various cancer types." (PMID 30513726, 2018). "As it is well known that cell mobility depends on the restructuring of the actin cytoskeleton and is essential for the process of metastasis, the authors propose here, like other authors, to study Nox4 as a drug target in cancer therapy." (PMID 30084091, 2018).
cancer (continued). "A statistically significant upregulation of NOX4 expression was found in multiple human cancers (P < .001), strongly correlating with myofibroblastic-CAFs (r = 0.65–0.91, adjusted P < .001)." (PMID 28922779, 2018). "The cancer tissue from both the Taylor cohort (P < 0.01) and the Grasso cohort (P < 0.0001) displayed a significant increase in NOX4 expression." (PMID 30459931, 2018). "In the two cancer cell lines used by us, Nox4 was exclusively seen in the ER (see Results and Discussion section)." (PMID 28620580, 2017). "NOX1 and NOX4, and the common subunit P22PHOX (encoded by CYBA) are, in contrast, activated in cancer cells and have been associated with keratinocyte-specific activity." (PMID 28122935, 2017). "Our result also warrants the exploration of methods to reverse the methylation of the Nox4 promoter as a possible cancer therapy." (PMID 27895046, 2017). "We now wanted to extend this finding by studying the human NADPH oxidase Nox4, which is involved in the pathomechanism of human cancer cells." (PMID 28620580, 2017). "These facts must be given careful consideration in the development of Nox4 as a target for cancer therapy." (PMID 28620580, 2017). "Among the members of NOX family, NOX4 is the most frequently expressed NOX isoform in terms of its relevance with cancer." (PMID 28422720, 2017). "Future studies will be required to investigate the behavior of Nox4 expression in other types of cancers." (PMID 27895046, 2017). "In the present study, DNA methylation of Nox4 is observed, with implications for Nox4 as a potential therapeutic target for liver or other cancers." (PMID 27895046, 2017). "Previous studies showed that NOX4 is upregulated in many cancers such as glioma, melanoma and thyroid cancer." (PMID 28099519, 2017). "We provide the first evidence that the NADPH oxidase isoform, NOX4, is a novel energetic sensor within the mitochondria, which serves as a checkpoint to couple mitochondrial energy metabolism to drug resistance in cancer cells." (PMID 29051480, 2017). "As this inhibition blocks cell mobility and, therefore probably metastasis, in one of the two cell lines studied here, we suggest to study Nox4 as a drug target in cancer therapy." (PMID 28620580, 2017). "This role of NOX4 in supporting active glycolysis in cancer cell metabolism was previously unrecognized." (PMID 28232723, 2017). "Meanwhile, NOX4 promoted cancer cell proliferation and apoptosis, migration and invasion by regulating the expression of relevant genes." (PMID 28422720, 2017). "Overexpression of NOX4 has been demonstrated in various cancers and in animal models, concomitant with the development of spontaneous fibrosis induced in genetically modified mouse models and with CCl4." (PMID 27895046, 2017). "Cellular events, such as cancer, which switch ATP production to aerobic glycolysis in the cytosol, thereby reducing ATP levels in the mitochondria relieves the breaks leading to NOX4 activation." (PMID 29051480, 2017). "NADPH oxidase 4 (NOX4) is a redox active, membrane-associated protein that contributes to genomic instability, redox signaling, and radiation sensitivity in human cancers based on its capacity to generate H2O2 constitutively." (PMID 28578276, 2017). "Recent reports indicate that NOX4 regulates cancer cell proliferation by regulating the PI3K pathway." (PMID 28099519, 2017). "Having established the ability of our monoclonal antibody to detect low levels of NOX4 in an endogenous system, we focused our studies on an immunohistochemical examination of NOX4 expression in human cancers." (PMID 28578276, 2017). "Together, we provide the first evidence that NOX4 functions as a mitochondrial energetic sensor and serves as a novel metabolic checkpoint, coupling the metabolic switch to cancer cell survival." (PMID 29051480, 2017).
cancer (continued). "Patients with high NOX4 expression showed a significantly shorter cancer-specific survival than those with a low level of NOX4 expression (log-rank test, P = 0.0003), clearly demonstrating that high NOX4 expression was associated with a shorter survival rate." (PMID 28422720, 2017). "Given the differential expression of Nox4 in several cancer cell types, therapies targeting Nox4 specifically show promise when combined with existing antimetabolites or cytotoxic drugs." (PMID 24583638, 2014). "The expression of these genes was significantly higher in stromal components, compared to epithelial cancer cells, with NOX4 showing the most pronounced differences (p = 0.04)." (PMID 24598828, 2014). "NADPH oxidase 4 (NOX4) is deregulated in various cancers and involved in cancer proliferation and metastasis." (PMID 24946933, 2014). "To better understand how RV induces ROS generation in cancer cells, we investigated if RV treatment has any impact on the expression of Nox1, Nox2, Nox3, Nox4 and Nox5 in NSCLC cells." (PMID 23533664, 2013). "This is the first report demonstrating that ROS generation through NOX4 contributes to an early step of urothelial carcinogenesis and cancer cell survival." (PMID 22032647, 2011). "Cycling hypoxia-induced ROS via Nox4 is a critical aspect of cancer biology to consider for therapeutic targeting of HIF-1 activation and cancer progression in GBM." (PMID 21935366, 2011). "Similarly, the role of NOX4 in generating ROS contributes to cellular signaling and survival, potentially affecting cancer progression." (PMID 40061897, 2025). "Erlotinib, an EGFR-TKI, also has the potential to induce OS in cancer cells by upregulating NOX-4." (PMID 40563358, 2025). "Therefore, a thorough exploration of the functional significance and specific mechanisms of NOX4 in cancer is crucial for the development of new treatment modalities." (PMID 38663913, 2024). "Elevated NOX4 expression significantly correlated with poor overall survival in several cancers." (PMID 38663913, 2024). "The prognostic significance of NOX4 in cancer is also gradually gaining attention." (PMID 38663913, 2024). "By elucidating the role of NOX4 in tumorigenesis, researchers aim to reveal new avenues for precision medicine, offering innovative approaches to address the multifaceted challenges posed by cancer." (PMID 38663913, 2024). "Furthermore, the association with established biomarkers for predicting immune checkpoint blockade response outcomes positions NOX4 within the intricate network of immune responses in cancer." (PMID 38663913, 2024). "Dysregulation of NOX4 expression in cancer has been observed across a spectrum of malignancies." (PMID 38663913, 2024). "Therefore, NOX4 inhibitors that are currently explored for the treatment of diseases such as fibrosis and certain cancers need to be verified for cardiovascular side effects." (PMID 39456432, 2024). "During normal conditions, OXPHOS produces ATP in mitochondria and normally hinders NOX4‐derived ROS, whereas during metabolic reprogramming of cancer cells and switching to glycolysis, ATP is generated in the cytosol and mitochondrial ATP homeostasis is disrupted, which leads to NOX4 activation." (PMID 38151790, 2023). "Inhibition of NOX4 (which presumably generates only H2O2) potentiates cancer immunotherapy." (PMID 36831432, 2023). "NOX4 is overexpressed also in other cancer cells and tissues, including renal carcinoma cells." (PMID 36768405, 2023). "NOX4 has been identified as a biomarker and therapeutic target for a variety of human cancers." (PMID 36915111, 2023). "However, a comparative analysis of NOX4 at the protein level in malignant and non-malignant tumors is missing." (PMID 37504283, 2023). "We deleted the cancer biomarker NOX4 using three novel genetic knockout (KO) methods." (PMID 38012557, 2023). "NOX4 is involved in almost every process of the occurrence, development and metastasis of cancers." (PMID 36874093, 2023).
cancer (continued). "Interestingly, in NOX4 knockout cancer cells, the expression of HIF1α-targeting genes, such as SLC2A1, encoding a glucose transporter, is prevented, thereby supporting the relevant role of NOX4-mediated metabolic reprogramming." (PMID 36768405, 2023). "NOX4 is a mediator of TGFb-RHO-ROCK-stimulated c-Jun N-terminal kinase (JNK) activation, which increases the expression of myofibroblast differentiation-related genes implicated in cancer progression and survival." (PMID 36614301, 2023). "Moreover, PAG can attenuate the TGF-β-induced NOX4-derived ROS which are in general known to lead to genomic instability and trigger signaling cascades promoting cell migration and invasion in cancer." (PMID 37300955, 2023). "At the same time, NOX4, as a ROS producing enzyme, is the downstream target of TGF-β1 and the regulatory center of cancer-associated fibroblast phenotype in many cancers, and promotes cancer-associated fibroblast (CAF) activation in tumors, with strong CAF specificity." (PMID 36874093, 2023). "Among them, NOX4 plays an important role in the occurrence of cancer." (PMID 35528617, 2022). "Elevated NOX4 mRNA and protein levels have been identified in cancers of diverse origins." (PMID 35269843, 2022). "NOX4 is the most frequently overexpressed isoform of NOX in cancer cells." (PMID 35180871, 2022). "Therefore, the purpose of this study was to systematically investigate the prognostic value of NOX4 expression in cancer patients." (PMID 35265227, 2022). "Additionally, clinical trials should be accelerated to evaluate the therapeutic effects of more novel NOX4 inhibitors in different cancer types." (PMID 35646942, 2022). "We found that NOX4 expression is related to prognosis in cancer patients." (PMID 35265227, 2022). "Thus, we conducted this meta-analysis to comprehensively understand the prognostic value of NOX4 expression in cancer patients." (PMID 35265227, 2022). "Moreover, NOX4 activation and ER stress lead to increased ROS in cancer cells, which play a key role in regulating tumor cell hyperproliferation." (PMID 35799889, 2022). "Lastly, NOX4-mediated ROS modulates diverse aspects of cancer development, other than metabolic adaptation, most notably the signaling of tyrosine kinase receptors and oncogenes that are often driving forces behind cancer cell proliferation." (PMID 35269843, 2022). "In addition, NADPH oxidase 4 (NOX4) is a common regulator of myofibroblast accumulation in many human cancers." (PMID 35740594, 2022). "It has been also reported that serum starvation increases stemness of cancer cells, thus it can be concluded that NOX4 may involve multiple alterations for adaptation to serum starvation, not even limited to this stress." (PMID 35396551, 2022). "NOX4–autophagy signaling is involved in tuberculous fibrosis-induced cancer progression." (PMID 33567693, 2021). "NOX4KO/PBS/KLN205 mice (NOX4 KO mice with KLN205 cancer cell injection after BCG treatment) showed a reduced number ofclusters of squamous lung cancer cells and decreased expression of Ki67 compared to NOX4WT/BCG/KLN205 mice (NOX4WT mice with KLN205 cancer cell injection after BCG treatment)." (PMID 33567693, 2021). "Since NOX4 is the strongest correlate of genetic programs of cancer progression, we explored factors that could further enhance or alter this association." (PMID 33557266, 2021). "Moreover, Uchl1 promotes H2O2 production by upregulating NADPH oxidase 4 (NOX4) activity through deubiquitination in the migration process of cancer cells, as well as in angiogenesis." (PMID 33967677, 2021).
cancer (continued). "Interestingly, NOX2 (encoded by CYBB) seems to have similar, although less striking, correlation patterns to NOX4 with all the cancer progression-related markers we surveyed." (PMID 33557266, 2021). "Moreover, the NOX4 blockade with siRNA suppressed the growth of cancer cells in an in vivo mouse orthotopic model." (PMID 34885171, 2021). "Pharmacological blockade of NADPH oxidase 4 (nox4), a key regulator of reactive oxygen species in muscle, significantly abrogated cancer cachexia in mice; targeting the SIRT1-nox4 axis seems to be an effective therapeutic intervention for mitigating cancer cachexia." (PMID 34262449, 2021). "We hypothesized that TGF-β1 drives metabolic reprogramming and aggressive cancer by enhancing NOX4 activity." (PMID 34257808, 2021). "Here, we began by exploring whether NOX4 expression is related to cancer progression by examining NOX4 mRNA levels relative to histopathological stages." (PMID 33557266, 2021). "Specifically targeting CAF NOX4 could re-sensitize CAF-rich tumors to anti-cancer vaccination and anti PD-1 checkpoint inhibition by reshaping CAF-regulated immune microenvironment." (PMID 32630174, 2020). "The diverse role of Nox4 is illustrated in the setting of cancer." (PMID 30737851, 2019). "Furthermore, using human urothelial carcinoma cell lines in culture, it has been demonstrated that NOX4 silencing reduced ROS generation and suppressed cancer cell growth via p16-dependent cell cycle arrest at the G1 phase." (PMID 31191796, 2019). "Furthermore, H2O2 induced NOX4-derived ROS signaling activation which, in turn, promotes cancer progression by inducing EMT, inhibiting apoptosis or promoting cell invasion." (PMID 30237423, 2018). "Nox4 expression seems to play a major role in all phases of cancer development (initiation, growth, epithelial to mesenchymal transition, cell migration, metastasis) and even in oncogene-induced senescence triggered by the oncogenic version of the Ha-ras proto-oncogene." (PMID 30084091, 2018). "Some previous studies have identified the biochemical links between Nox4 and cancer through several mechanisms, including angiogenesis, inflammatory cytokines, apoptosis resistance, histone modification, transforming growth factor-β and epidermal growth factor receptor pathway and so forth." (PMID 30513726, 2018). "Intriguingly, NOX4 expression was also repressed by ROS inhibition or p38 inhibition, which are downstream molecules of NOX4, suggesting that a positive feedback loop was formed to sustain cancer cell death in A375 cells." (PMID 30523245, 2018).